IL6 (interleukin 6)
Diseases named in the same sentence as IL6 in open-access papers (continued):
Sharing a sentence is not in itself a finding about the gene and the disease.
COVID-19 (continued). "In fact, the pattern of pro-inflammatory cytokines induced in COVID-19 is similar to target cytokines for RA treatment; Several studies have showed that primary epithelial cells are infected with COVID-19, serve as a source of cytokines, and secrete TNF-α., IL-6, IL-1 and IL-8." (PMID 39211019, 2024). "A long-lasting cytokine signature with high levels of interleukin (IL)-1, IL-6, and tumour necrosis factor (TNF) may be responsible for many of the clinical signs of Post-acute sequelae of COVID-19 (PASC) and may originate in the macrophage compartment, according to one study." (PMID 38544825, 2024). "Also, a recent prospective observational study highlighted lower IL-6 and IL-8 levels in the early phase (days 1–4) of COVID-19-ARDS compared to non-COVID-19-ARDS." (PMID 38536545, 2024). "Likewise, IL-6 and TNF-α were considerably upregulated in COVID-19 patients." (PMID 38849961, 2024). "This confirmed other reports that although COVID-19 vaccination does not affect plasma IL-6 levels, the salivary levels of sACE2 may reflect an inflammatory condition, which can be accelerated by periodontitis." (PMID 39917640, 2024). "Other pertinent COVID-19 biological markers such as D-dimer, IL-6, pulmonary function tests, and chest CT scans were not included as variables in this study, which might have helped establish the utility of VCO." (PMID 38282651, 2024). "The development of COVID-19-associated nephropathy (COVAN), in particular, may be mediated through IL-6 and signal transducer and activator of transcription 3 (STAT3) signaling, suggesting a direct connection between the COVID-19-related immune response and the development of chronic disease." (PMID 40012912, 2024). "However, as none of the clinical trials on anti-IL-6 therapy in COVID-19 used sublingual microscopy to estimate the eGC properties, we are currently unable to estimate the effect of anti-IL-6 treatment on eGC dimensions in vivo." (PMID 38598083, 2024). "Given the fact that IL-6 is a key mediator of the “cytokine storm” that leads to acute respiratory distress syndrome (ARDS) and multi-organ dysfunction in severe COVID-19, it can be assumed that such a distribution of tRF types may be due to the condition the patient underwent." (PMID 39459595, 2024). "However, application of immunomodulatory drugs including glucocorticosteroids or anti-IL-6 treatment is not standard of care for severe influenza but for severe COVID-19, which may contribute to the elevated risk of pulmonary aspergillosis in critically ill COVID-19 patients." (PMID 38217742, 2024). "They found that 6-MSITC reduces the production of proinflammatory cytokines, such as IL-6 and TNF-α, and lowers the adhesion of immune cells to endothelial cells, which are crucial factors in the development and progression of inflammation and cytokine storms in patients with COVID-19." (PMID 39459194, 2024). "It is possible that outcomes may have differed with higher baseline use of IL-6 inhibitors, though previous studies of patients hospitalized with COVID-19 (regardless of severity) have not shown any survival benefit of tocilizumab in addition to SOC." (PMID 39522090, 2024). "It has been shown that some parameters related to inflammation, such as TNFα, IL-6, interleukin-8 (IL-8), interleukin-10 (IL-10), CRP, white blood cell count (WBC), lymphocyte count (LC), and the number of neutrophils (NC) are correlated with the severity of COVID-19." (PMID 39335569, 2024). "There is a negative correlation between NEAT-1 and IL6 in COVID-19 patients." (PMID 39729489, 2024). "Compared with those in healthy volunteers, the concentrations of interleukin (IL)-6 (median 27.6 pmol/L), IL-8 (1045.1 pmol/L), IL-17A (0.8 pmol/L), IL-25 (1.5 pmol/L), and IL-31 (42.3 pmol/L) were significantly greater in the ELF of COVID-19 patients than in that of volunteers." (PMID 38654351, 2024).
COVID-19 (continued). "However, we observed a substantial increase in IL-6 and CRP levels associated with the severity of COVID-19, while no such trend was observed for IL-1β and TNF-α." (PMID 39188881, 2024). "One of the objectives of our study was to molecularly and biologically evaluate the levels of pro-inflammatory cytokines (IL-1, IL-6) and anti-inflammatory cytokines (IL-4, IL-10) in the appendixes of children with COVID-19, considering the lack of data on this in the global literature." (PMID 38397914, 2024). "IL-6 and SP-D are correlated with both BMI and age, while complement C5a, E-selectin, ICAM-1, MCP-1, Tie-2, and vWF levels were associated with age in patients with critical, but not severe COVID-19." (PMID 39507250, 2024). "However, during the pandemic, the requests for IL-6 detection increased exponentially, but the ELISA method was no longer the method suitable for the urgent context of COVID-19." (PMID 38617587, 2024). "The IL-6 cytokine serves as a marker for COVID-19 severity, showing a negative correlation with age in patients infected with the Delta variant and a positive correlation with CRP, COVID-GRAM score, total leukocyte count, and neutrophils in those infected with the Omicron variant." (PMID 39281077, 2024). "Considering the pronounced inflammatory response in COVID-19 and CDI infections, with elevated levels of IL-6, TNF-α, IL-1β, and IP-10, as well as the reported dysbiosis, FMT could play a crucial role in the treatment of CDI or more severe conditions like COVID-19 and C. difficile co-infections." (PMID 39432486, 2024). "IL-6 plays an important role in these processes and could be pharmacologically improved through JAK1 inhibitors that are under evaluation for the treatment of severe COVID-19." (PMID 37376587, 2023). "Given that a similar proinflammatory response is also observed in COVID-19, the severe forms of COVID-19 are most likely attributable to the hyperactivation of NF-κβ that regulates the synthesis and release of proinflammatory cytokines, such as TNF-α and IL-6, in severe COVID-19 patients." (PMID 37047115, 2023). "In human cases of COVID-19 or dengue, IL-6 levels are not as high as those in mice." (PMID 37939119, 2023). "Severe COVID-19 in controls, but not SOT recipients, was associated with a marked increase in several canonical proinflammatory serum cytokines and chemokines (e.g., IL6, CCL7, and CXCL9)." (PMID 38196658, 2023). "IL-6, neutrophil count, % neutrophils, NLR, PLR, CRP, AST, and urea rose with the increased severity of the SARS-CoV-2 infection, and lymphocyte count, % lymphocytes, eosinophil count, % eosinophils, hemoglobin decreased with the increased severity of COVID-19." (PMID 36838284, 2023). "In a special cohort of 287 COVID-19 patients, 20.2% of patients were reported to have thyrotoxicosis, having TSH levels below the normal range, and multivariate analysis revealed an opposite connection between TSH values in serum and cytokine interleukin-6 (IL-6 levels)." (PMID 37212057, 2023). "Here, we did not assess the confounding effects of anti-COVID-19 treatments, such as anti-viral, systemic corticosteroid, or interleukin-6 blockade; however, these factors may affect the development of post-acute sequelae of SARS-CoV-2 infections." (PMID 38049876, 2023). "Indeed, we observed a positive association between 2-AG production and IL-10 and lymphocyte counts and a negative correlation with different COVID-19 markers of hyperinflammation, such as IL-6, sTREM-1 and neutrophil counts." (PMID 36851787, 2023). "A considerable increase was found in the number of tests related to the management of COVID-19 patients, including IL-6 (+22,350.9%, which was not available in most laboratories until 2020); D-dimer (+617.2%), troponin (+46.8%) and arterial blood gas (+35.9%), p<0.001 for all." (PMID 37363429, 2023).
COVID-19 (continued). "While our COVID-19-positive group were not hospitalized and therefore classified with ‘mild’ illness, it is likely that IL-6 and other pro-inflammatory cytokines reach high levels during COVID-19 infection, well in excess of levels associated with well-known risk factors such as elevated BMI." (PMID 36995412, 2023). "Indeed, patients with complicated forms of COVID-19 had nearly threefold higher serum IL-6 levels than those with noncomplicated forms of the disease." (PMID 36857362, 2023). "Interestingly, DNase I could prevent systemic inflammation in some COVID-19 patients, including the reduction of pro-inflammatory cytokines TNF-α and IL-6." (PMID 36864506, 2023). "However, the expression of IL6 and TNF, well-known markers associated with severity in COVID-19, was lower in non-classical monocytes in Yh034 than in Yh002/Yh004, parallel to the clinical status of each patient at the time point." (PMID 36732528, 2023). "This patient did not experience severe inflammation at the time of COVID-19, but our data nevertheless highlight an enhancement of inflammatory cascades (TNF/NF-κB and IL-6/JAK/STAT3) in STAT2 deficiency, both in the basal state and during acute COVID-19, mediated predominantly by neutrophils." (PMID 36976641, 2023). "The pro-inflammatory cytokines IL-6 and IL-18 were not significantly different in the disease group compared to those in the healthy group, suggesting that acute inflammation subsided while COVID-19 was cured." (PMID 37422499, 2023). "COVID-19 vaccination leads to an increase in IL-6 for at least 1 day, but no longer than 4 weeks." (PMID 36835948, 2023). "This phenomenon may account for the notable decrease in levels of IL-6 and IL-17 in COVID-19 patients experiencing GI symptoms, resulting in reduced mortality rates compared to COVID-19 patients lacking these symptoms." (PMID 37376531, 2023). "MHLA-DR expression was strongly reduced by plasma from COVID-19 patients with immune dysregulation but not healthy controls; the effect could be partially restored by the addition of the IL-6 blocker Tocilizumab." (PMID 36834656, 2023). "In contrast to COVID-19(+) TV, highly expressed in the COVID-19(-) PU control group included MHC class II antigen processing (HLA-DRB3/4, HLA-DPB1, HLA-DRA, CIITA, and CD74), mast cell degranulation (TPSAB1/B2), B cell activation (CXCL13, BLNK, IL-6) and histone modification (USP21, HIST1H4E)." (PMID 37026002, 2023). "Indeed, circulating levels of IL-6 are higher in hospitalized COVID-19 patients with complications compared to patients without complications." (PMID 37686837, 2023). "In addition, IL-6 was further combined with Y-MOF@S2 leading to the hybrid sensing platform Y-MOF@S2@IL-6, resulting in a specific recognition of oseltamivir among the potential COVID-19 drugs." (PMID 37234896, 2023). "As a majority of COVID-19 do not display signs of severe illness at inception of their treatment, National and International guidelines have advised against preventative anti-inflammatory treatment with corticosteroids or IL-6/JAK/STAT inhibitors." (PMID 37214455, 2023). "Second, information about factors which could influence IL-6 levels in the blood, such as recent vaccinations or re-infection with COVID-19, were not collected from the participants." (PMID 36835948, 2023). "Significant differences in cytokine levels (e.g., IL-6) and plasma protein levels (e.g., C-reactive protein, CRP) were reported among different groups of COVID-19 patients, and both indices were considered potential biomarkers for the diagnosis, progression, and prognosis of COVID-19." (PMID 37894092, 2023). "Increased plasma levels of IL-1β, IL-6, and IL-8 in patients with COVID-19 also has a negative effect on the RBCs’ ultrastructure and induces signs of eryptosis, a form of suicidal death of RBCs, that exhibits an increased tendency of adhering to ECs as well as platelets, contributing to thrombosis." (PMID 36979908, 2023).
COVID-19 (continued). "A non-adjusted cox regression among patients with COVID-19 depending on levels of IL-6." (PMID 37960722, 2023). "Previous studies found that thymosin drugs could inhibit the inflammatory/activated state of monocytes in the treatment of COVID-19 by reducing the release of proinflammatory mediators such as TNF-α, IL-6 and IL-8, and promote the generation of anti-inflammatory cytokines such as IL-10." (PMID 37743481, 2023). "We found that pro-inflammatory markers such as IL-6 (at 24 h) and hematological markers such as NLR (at 24 and 72 h, respectively) were independent predictors of 28-day mortality in patients with severe COVID-19 living at high altitude in a low-resource setting." (PMID 36675573, 2023). "In fact, a few studies reported a decrease in IL-1β and/or TNF-α but not IL-6, which explains why IL-6 could be the sole determinant of severity in COVID-19." (PMID 37106750, 2023). "Furthermore, a significant increase in the frequency of CD14high CD16+ monocytes producing IL-6 was reported in the peripheral blood of COVID-19 patients in the ICU compared to those without ICU hospitalization." (PMID 36793739, 2023). "However, why did anti-inflammatory therapies (anti-IL-6, glucocorticoids) improve survival of COVID-19 patients, if there was no cytokine storm?" (PMID 36851312, 2023). "Several studies have documented significant elevation in inflammatory cytokines (IFN-γ, TNF-α, IL-6) in severe COVID-19 compared to non-severe cases that are consistent with this study and may be proposed as prognostic markers." (PMID 38057707, 2023). "Our results do not support a direct association between IL-6 and PCT serum levels and mortality rate in severe COVID-19 patients but suggest that CRP may be a more reliable surrogate of COVID-19 patient’s outcomes." (PMID 37109370, 2023). "The role of ∝2-M in COVID-19 has been proposed based on its versatility; specifically, in its tetrameric form, it is able to inhibit all four classes of proteases, while in its dimeric form, it shows increased interaction with mediators of inflammation, such as TNF-∝, Il-2, and IL-6." (PMID 37371071, 2023). "Studies have shown that patients critically ill with COVID-19 have higher serum concentrations of proinflammatory cytokines and chemokines, including granulocyte colony-stimulating factor, monocyte chemoattractant protein-1, TNF-α, IL-6 and IL-1β, than healthy individuals." (PMID 36979888, 2023). "Furthermore, the levels of MIP-1α, IL-6, and IL-2 were not altered throughout the observation period in the COVID-19 group between different time points." (PMID 37034572, 2023). "IL-6 could not to be test in serial examination because regulation from hospital to limit the contact with COVID-19 patients." (PMID 37889917, 2023). "In addition, we provided several potential targets for COVID-19 AKI treatment, mainly IL6, VEGFA and RELA, which may help to develop new therapeutic strategies." (PMID 37274117, 2023). "Thus, IL-6 concentration, C reactive protein level and platelet count allowed to discriminate between death and discharge in patients hospitalized with severe COVID-19 only during the first but not the second wave." (PMID 36817433, 2023). "Thus, we hypothesized that IL-6 might represent the common denominator of both acute respiratory failure and SIAD-related hyponatremia in COVID-19 patients." (PMID 36284058, 2023). "The increase in the severity of COVID-19 showed elevated levels of WBC count, neutrophil%, platelet count, neutrophil/lymphocyte ratio, serum ferritin, D-dimer, C-reactive protein, procalcitonin, interleukin-6, and lactate dehydrogenase, and decreased lymphocyte and monocyte percentages." (PMID 37016651, 2023). "In addition, IL-6 levels in COVID-19 and AKI non-survives and survives were 129.33 (99.04–166.88) and 83.34 (77.88–99.06), respectively." (PMID 37889917, 2023).
COVID-19 (continued). "Moreover, critically ill children with COVID-19 could develop AKI, and elevated IL-6 is a common finding in these patients, emphasizing the role of cytokine storm as an underlying cause of acute renal injury." (PMID 37313354, 2023). "Importantly, both IL-6 and MCP-1 are considered pro-inflammatory and prognostic of persistent and acute inflammatory dysregulation in chronic conditions and infectious diseases such as COVID-19." (PMID 37049389, 2023). "IL6 was found to modulate several pathways related to H5N1 infection, such as the Toll-like receptor signalling pathway, Influenza A, TNF signalling pathway, Coronavirus disease—COVID-19, NOD-like receptor signalling pathway, and cytosolic DNA-sensing pathway, in our study." (PMID 37515084, 2023). "The purpose of this study is to investigate any probable IL-6 serum titer difference in COVID-19 patients with vertigo (V+) or without vertigo (V-) admitted to the COVID-19 internal medicine departments of Attikon University Hospital, Athens, Greece, within 12 months." (PMID 36942191, 2023). "However, in the case of severe COVID-19 patients, a retrospective study has found significantly reduced IL-6 levels in LMWH treated patients, prompting the suggestion that this treatment may partially attenuate COVID-19 induced CS." (PMID 37259415, 2023). "Similarly, in this study, according to the forest plot results, IL-6 levels were found to be high in patients with long COVID-19 compared with healthy individuals and those without PASC." (PMID 37095536, 2023). "The present meta-analysis revealed that COVID-19 non-survivors had higher levels of IL-6." (PMID 36747045, 2023). "IL-6 plays a crucial role in the shift from mild inflammation to severe hyperinflammatory conditions, including cytokine release syndrome (CRS), acute respiratory distress syndrome (ARDS), and lung damage, which can lead to high mortality in critically ill COVID-19 patients." (PMID 38005862, 2023). "Interleukin - 6 is an indication of severe cytokine storm in many cases such as chimeric antigen receptor-T (CAR-T) cell therapy, malignant tumor progression, autoimmune disorders, inflammatory diseases and COVID-19, which could be life-threatening." (PMID 37488213, 2023). "Interestingly, some of the main exerkines, i.e., cytokines that are released during and after exercise, such as IL-6, IL-8, IL-1ra, or TNF-alpha, are the very same ones that are elevated in COVID-19, raising the possibility that common molecular mechanisms are activated." (PMID 37234053, 2023). "However, routine treatment according to national guidelines for COVID-19 did not change IL-6 values in the control group." (PMID 37365605, 2023). "IL-6, neutrophil count, % neutrophils, NLR, PLR, CRP, AST, and urea increased with the severity of the SARS-CoV-2 infection, and the lymphocyte count, % lymphocytes, eosinophil count, % eosinophils, and hemoglobin decreased with the increased severity of COVID-19." (PMID 36838284, 2023). "Some severe COVID-19 patients have laboratory findings of an overt inflammatory response, cytokine release syndrome, continuous fevers, elevated inflammatory markers (e.g. CRP and ferritin), and upregulated levels of pro-inflammatory cytokines (e.g. TNF alpha, IL-1, and IL-6)." (PMID 36914565, 2023). "In another uncontrolled exploratory study in 77 patients with moderate COVID-19, treatment with nebulized IFN-a2b significantly reduced the duration of detectable virus in the upper respiratory tract and in parallel reduced duration of elevated blood levels for the inflammatory markers IL-6 and CRP." (PMID 38077399, 2023). "Several proinflammatory cytokines such as tumor necrosis factor-alpha (TNF-α), interleukin (IL)-6, IL-2, IL-7, and IL-10 are involved in the development of cytokine release syndrome (CRS), which then contributes to the high morbidity and mortality of COVID-19 including ARDS." (PMID 37047115, 2023).